IGF1R (insulin like growth factor 1 receptor)
Diseases named in the same sentence as IGF1R in open-access papers (continued):
Sharing a sentence is not in itself a finding about the gene and the disease.
tumor (continued). "In contrast to SSTR2, IGF-1R has been implicated in tumor growth, invasion, and metastasis, and the binding of IGF-1 and IGF-1R triggers a proliferative and anti-apoptotic signaling cascade." (PMID 39238765, 2024). "In the cell–matrix interaction, decorin and lumican represent small leucine-rich proteoglycans and critical matrix constituents reported to modulate the functions of tyrosine kinase receptors in tumor cells, including IGF1R and IR-A." (PMID 38892104, 2024). "Simultaneously, the Ada-BPY component generated cytotoxic ROS through photodynamic process, directly inhibiting tumor cell growth and disrupting IGF1R bypass signal activation." (PMID 39321294, 2024). "In the development of malignant tumors in humans, the signaling level of the IGF/IGF-1R pathway plays a pivotal role in promoting cell transformation, tumor cell proliferation, resistance to apoptosis, and metastasis." (PMID 38665430, 2024). "By binding to IGF1R mRNA with m1A modification, YTHDF3 enhances the degradation of IGF1R mRNA, and subsequently reducing the expression of matrix metalloproteinase 9, an enzyme involved in extracellular matrix remodeling and tumor cell invasion." (PMID 39687616, 2024). "This indicates that paracrine signaling between stromal-produced IGF ligands and IGF-1R on tumor cells is crucial for secondary tumor expansion." (PMID 39273251, 2024). "Upregulation of IL-4/IL-4R signaling in TAMs results in their increased secretion of insulin-like growth factor (IGF-1), which, upon binding to IGF-1 receptor (IGF-1R) on tumor cells, upregulates the PI3K pathway, promoting tumor growth and malignancy." (PMID 38254796, 2024). "Our data demonstrate that oHSV therapy induces activation of the IGF1R signaling pathway, potentially sensitizing virus-infected tumor cells to IGF1R-targeting drugs." (PMID 38853689, 2024). "Taken together, these results show that PRKCSH contributes to the adaptation of tumor cells against TNFSF cytotoxicity by increasing the half-life of IGF1R, which is involved in tumor resistance to antitumor immunity and various cancer therapeutics." (PMID 38200153, 2024). "In GBM, ERBB3, IGFR1R and TGFBR2 were positively correlated with PDGFR, and combining a PDGFR inhibitor with either an ERBB3 inhibitor or an IGF1R inhibitor resulted in a more significant reduction in tumour growth than each inhibitor alone." (PMID 39272879, 2024). "RNA-seq data analysis indicated that anti-PD-1/IGF1R led to a more potent immune response, as reflected by altered gene expression levels related to anti-tumor immune response, compared with either treatment alone." (PMID 39450263, 2024). "We demonstrated that IGF1R inhibition elicits a potent antitumor immunity and that the combination with PD-1 blockade leads to tumor regression in EOC mice." (PMID 39450263, 2024). "IGFBP7 expressed by tumor endothelial cells suppresses IGF1R signaling and the stem-cell-like property of tumor cells." (PMID 38576482, 2024). "As a result, most studies describing intracellular IGF-1R signaling have been conducted in tumor cells, which poses a cautionary note when translating these observations to their healthy counterparts." (PMID 39638246, 2024). "In this study, we found that overexpression of CBX and IGF-1R, respectively, resulted in a remarkable increase in sphere-formation capacity, proliferation ability, and drug resistance of tumor cells." (PMID 38413558, 2024). "PCAT6 stabilizes the mRNA of IGF1R through its interaction with IGF2BP2 and IGF1R, activating pathways that encourage tumor growth and metastasis." (PMID 38249783, 2024). "Specifically, IGF2BP3-positive extracellular vesicles sustained the migration and invasive potential of recipient tumor cells as well as the expression of IGF1R and the downstream AKT pathway." (PMID 38892104, 2024).
tumor (continued). "Among them, the RNA-binding protein IGF2BP3, which sustains the translation of IGF1R in the cytoplasm of tumor cells, was encapsulated in extracellular vesicles extracted from Ewing sarcoma cell lines." (PMID 38892104, 2024). "Preclinical studies have shown that Linsitinib effectively inhibits the activity of both IR and IGF-1R in tumor cells and tumor xenograft models." (PMID 38331804, 2024). "have observed that the IGF1/IGF1R axis inhibition enhanced the efficacy of immunogenic chemotherapy, which correlated with an increase in tumor infiltrating effector T cells and a decrease in T-regs, in breast tumor mouse models." (PMID 38420122, 2024). "It has been demonstrated that inhibition of IGF-1R enhances the occurrence of anoikis in tumor cells and reduces the number of tumor cells in the blood circulation of mice, thereby inhibiting tumor metastasis." (PMID 38342894, 2024). "At the molecular level, paclitaxel upregulated the RBFOX3 protein and circIGF1R in the tumor tissues, and downregulated IGF1R mRNA." (PMID 38191906, 2024). "In contrast, the IGF-1R exhibited a more dispersed staining pattern in all tumor tissue sections, with evidence of cytoplasmic and Golgi localization." (PMID 39608716, 2024). "The overexpression of IGF-1R during tumor development activates downstream signaling pathways such as AKT, ERK1/ERK2 and STAT3." (PMID 38686058, 2024). "Despite the significantly decreased tumor weight observed in combined group compared to IGF1R inhibitor group, the OS rate appears similar." (PMID 39450263, 2024). "At post-transcriptional levels, microRNAs (miRs), long non-coding RNAs (lncRNAs) and RNA-binding proteins, such as the family of N6-methyladenosine (m6A) readers RNA-binding proteins IGF2BPs, regulate the stability of IGF2 and IGF1R in tumor cells." (PMID 38892104, 2024). "In this study, we discovered a novel mechanism of resistance to oHSV therapy in which viral therapy-induced IGF2 expression and secretion activates IGF2/IGF1R signaling in tumor and TME cells." (PMID 38853689, 2024). "In the extracellular matrix, the integration of the IGF1R axis and integrin signaling strongly contributes to tumor progression." (PMID 38892104, 2024). "Combining IGF-1R inhibitors with trastuzumab, tamoxifen, or fulvestrant has shown enhanced anti-tumor effects in preclinical studies." (PMID 39273251, 2024). "IGF1R is a tyrosine kinase that is overexpressed in various types of tumor cells and plays an important role in the proliferation and survival of tumor cells." (PMID 38533261, 2024). "CAFs secrete high levels of the ligands IGF1 and IGF2, thereby promoting the tumor growth, migration, and invasion as well as drug resistance of IGF1R-expressing tumor cells." (PMID 38892104, 2024). "One study on IGF-1R expression in NSCLC found that treatment with IGF-1R TKIs exhibited significant anti-tumor activity in NSCLC cells with wild-type EGFR and KRAS." (PMID 38540176, 2024). "IGF1R plays a crucial role in facilitating cell growth and regulating apoptosis and substantially influences tumor development." (PMID 39771106, 2024). "The LLC, when transplanted into wild-type mice, led to multiple pulmonary metastases, while Igf1r KO mice showed a reduced tumor burden." (PMID 38255007, 2024). "It is noteworthy that IGF2 sends signals through IGF1R, one of the key receptor tyrosine kinases involved in tumor development." (PMID 39711843, 2024). "The promising results obtained from the IGV001 and VOKVAC phase 1 clinical trials are the demonstration that manipulating the tumor immune microenvironment through targeting the IGF1/IGF1R axis is safe and feasible." (PMID 38420122, 2024). "The analysis showed that IGF-1R expression was significantly higher in tumor tissue compared with paracancerous tissue from the same patient." (PMID 38342894, 2024).
tumor (continued). "In BC, miR-122 has been found to act as both a tumour suppressor, targeting the insulin-like growth factor 1 receptor, and as an oncogene, reprogramming glucose metabolism in the tumour microenvironment via exosome." (PMID 38820252, 2024). "It uses drugs such as IGF-1R or mTOR to inhibit tumor growth in order to achieve a therapeutic effect." (PMID 39445018, 2024). "Analysis of the tumors revealed that the combined anti-PD-1/IGF1R treatment led to a significant decrease in the mean tumor mass compared to mice treated with either the anti-PD-1 or the IGF1R inhibitor (34% and 40% decreases, respectively)." (PMID 39450263, 2024). "Inoculation of 4T1 tumor cells with IGF1R-knockdown CAFs into BALB/c mice resulted in increased infiltration and antitumor activities of CD8+ T cells, as well as reduced tumor growth compared with the control group." (PMID 39545420, 2024). "Further validation using in vivo models confirmed that overexpressing IR-A and IGF-1R promoted tumor cell growth, induced angiogenesis, and generated drug resistance." (PMID 38331804, 2024). "Nonetheless, the emerging role of the IGF1R pathway inhibition in regulating immunomodulation and boosting anti-tumor immunity appears to open new therapeutic opportunities for the IGF1R targeting agents." (PMID 38420122, 2024). "Clinical data with anti-IGF-1R mAbs and TKIs show that these targeting approaches are feasible and can induce strong anti-tumor activities in several tumor types, including rare tumors refractory to standard therapies." (PMID 39273251, 2024). "In BC patients, miR-122 has been identified as a tumour suppressor that targets the insulin-like growth factor-1 receptor." (PMID 38820252, 2024). "A study on miRNAs confirmed this finding, demonstrating that the downregulation of miR-448 expression in HCC promotes tumor progression through the reversal of IGF-1R-mediated glycolysis and cell survival inhibition." (PMID 38816668, 2024). "The expression levels of certain biomarkers, such as EGFR, HER2, mucin MUC1 and insulin-like growth factor-1 receptor (IGF1R), are reduced in healthy cells but elevated in tumor cells." (PMID 39840069, 2024). "IGF-1R is a cell membrane receptor and is known to play a critical role in the proliferation cascade, cancer cell development, tumor progression, and resistance to treatments." (PMID 38491424, 2024). "SUMOylation of IGF1R can alter downstream signal transmission efficiency, thus inhibiting tumor cell proliferation and migration." (PMID 39723246, 2024). "In this model, the loss of DACH1 is tumor cells enhances the secretion of IGF1, which in turn binds and activates the IGF1R and downstream signaling in TAMs." (PMID 38892104, 2024). "This synergistic effect induces the simultaneous dysfunction of immature IGF-1R and IR, thereby enhancing tumor suppression." (PMID 39199143, 2024). "EOC is an immunosuppressive disease, although there are limited data about the involvement of the IGF1R system in the anti-tumor immune response in the EOC microenvironment." (PMID 39450263, 2024). "In cancer, the IGF1/IGF1R axis appears to play a role in modulating DC activity toward an immature state with immunosuppressive and tumor-promoting activities." (PMID 38420122, 2024). "IGF-1R, a pivotal receptor tyrosine kinase, garners significance as a therapeutic focus across myriad tumor interventions." (PMID 38413558, 2024). "This conjugate selectively enters cancer cells via IGF-1R, showing promising anti-tumor activity in MCF-7 xenografts with fewer side effects compared to free MTX." (PMID 39273251, 2024). "They enhance the anti-cancer response by recruiting immune cells to tumor sites, providing a multifaceted approach to targeting IGF-1R in BC." (PMID 39273251, 2024).
tumor (continued). "Gaining a comprehensive understanding of the underlying mechanisms governing receptor abundance manipulation can offer valuable insights for the development of precise tools to target and regulate IGF1R levels specifically in tumor cells." (PMID 38182007, 2024). "Linsitinib, OSI-906, is an inhibitor of IGF-1R and has been reported to inhibit cell proliferation of several tumor cells." (PMID 39693285, 2024). "Accordingly, halting this feedforward loop of TAM recruitment and alternative activation through a combination of CSF-1R and IGF-1R inhibition leads to a further reduction in tumor progression in mice." (PMID 38254796, 2024). "This justifies laboratory studies to address gaps in knowledge concerning the roles of IGFBP7 in neoplasia, and the relevance of this protein to IGF-1R-targeting agents." (PMID 39362991, 2024). "Irradiated CAFs release IGF1, which mediates IGF1R/IR phosphorylation and activation of downstream signaling in tumor cells." (PMID 38892104, 2024). "IGF-1R activation seems to have an essential role in tumor cell proliferation of different tumor types, which has provided reason to incorporate anti-IGF-1R drugs in the frame of the disease management." (PMID 38375032, 2024). "Altogether, these observations indicate that IGF1R is at the apex of several signaling pathways directly controlling tumor cell proliferation and modulating the immune TME." (PMID 38420122, 2024). "Altogether, 23 of the 32 mice developed a tumor and ascites: 4 in the control group, 5 in the IGF1R inhibitor group, and 7 each in the anti-PD-1 and combined groups." (PMID 39450263, 2024). "The nuclear activity of IGF1R is prominent in cancer cells and often correlates with adverse clinical outcomes and tumor biological characteristics." (PMID 39404930, 2024). "Intriguingly, IR isoforms exhibit a more pivotal role in specific tumor tissues when compared to IGF1-R itself." (PMID 38331804, 2024). "IGF1R is an oncogene that promotes tumor cell proliferation, metabolism, and metastasis, and it has promising applications in combination therapy for tumors." (PMID 38982511, 2024). "IGF-1R expression levels correlated positively with venous invasion and liver metastasis, as well as with tumor size." (PMID 36835075, 2023). "IGF-1R signaling has also recently gained attention as a potential therapeutic target in human cancer, with IGF-1R inhibition expected to diminish tumor cell survival." (PMID 36900315, 2023). "To determine if greater anti-tumour activity would be observed in vivo, we tested the effect of targeting IR/IGF1R in a cell-line derived xenograft model of TNBC, using the HCC1143 cell line." (PMID 36920947, 2023). "IGF1R monoclonal antibodies and IGF1R-selective inhibitors are being tested for their abilities to suppress tumor metastasis and progression while also increasing tumor susceptibility to other biological treatments." (PMID 37854681, 2023). "Daily intraperitoneal injection of metformin in a subcutaneous PC‐3 xenograft model reduced tumour growth and IGF‐1R mRNA expression which further supports the finding that metformin targets IGF‐1R signalling to inhibit PCa growth." (PMID 36569495, 2023). "The proliferation and longevity of numerous tumor forms, particularly HNSCC, have been linked to the insulin-like growth factor-1 receptor (IGF-1R) and its ligands IGF-1 and IGF-2." (PMID 37205904, 2023). "Clinically, the differences above were reflected by the results of TMA and WB analysis, where upregulated protein expression of IGF1R was found in tumour tissues compared to para-neoplastic tissues." (PMID 36978187, 2023). "In preclinical studies, IGF1R inhibitors have demonstrated promising anti-tumor activity, particularly in combination with other cancer therapies." (PMID 37744271, 2023). "The Insulin Growth Factor-1 (IGF)-/Insulin-like Growth Factor-Receptor1 (IGF1R) pathway plays critical roles in the regulation of tumor cell metabolism, proliferation, survival, and angiogenesis." (PMID 37284192, 2023).
tumor (continued). "There are a number of tumor‐promoting factors in tumor cells such as IL‐17RB, IGF‐1R, MDR1, Bcl‐2, and HMGA2, among others, that can mediate resistance of cancer cells to DOX chemotherapy." (PMID 36684100, 2023). "We identified two genes, HDAC4 and IGF1R, in our pediatric CNS tumors that were both epigenetically and transcriptionally altered in comparison to non-tumor pediatric brain tissue." (PMID 36909536, 2023). "BMS-754807, an IGF1R/IR inhibitor, induces G2/M arrest in tumour cells and inhibits tumour cell proliferation." (PMID 38049741, 2023). "MiR-184 can act as a tumor suppressor in CRC by directly targeting insulin-like growth factor 1 receptor (IGF-1R)." (PMID 38001121, 2023). "A search revealed studies of the effects of IGF-1R inhibitors in preclinical in vivo assays, permitting calculation of the percentage of tumor growth inhibition." (PMID 37505498, 2023). "The secreted protein genes WNT5A, VEGFA, and SEMA3A, and the receptor genes AXL, TNFRSF10B and IGF1R were mainly expressed by tumor cells." (PMID 37823774, 2023). "IGF/IGF-1R signaling promotes tumor cell invasion and metastasis by regulating cell growth, survival, migration, and protein synthesis." (PMID 37305177, 2023). "Taken together, integrin-mediated close contact between T-ALL cells and tumor-associated myeloid cells plays an essential role in promoting the survival of T-ALL, in part by enabling activation of IGF1R signaling." (PMID 37805579, 2023). "In other cancers, integrins have been shown to interact with IGF1R to promote signaling that results in tumor survival, migration, and therapeutic resistance." (PMID 37805579, 2023). "Among them, “BMS-536924” and “linsitinib” are IGF-1R/IR inhibitors that can inhibit glucose metabolism in tumor cells and then exert anti-tumor effects." (PMID 36864522, 2023). "IGF1R is a pro-cancer indicator in the tumor microenvironment that promotes heterotopic transplantation and initiation." (PMID 37582734, 2023). "IGF1/IGF1R regulates cell proliferation, angiogenesis, metastasis, metabolism, tumor microenvironment, chemoresistance, stem cells enrichment, and amplification in cancer." (PMID 36774408, 2023). "In contrast, IGF1R activation in tumor cells is strictly dependent on Sdc1, even if IGF1 is present, and is therefore blocked by SSTNIGF1R." (PMID 36968227, 2023). "It was shown that either PYCR1 pY135 or IGF1R phosphorylation levels were increased in tumor tissues compared with the adjacent normal tissues." (PMID 37777542, 2023). "We have previously shown that tumor-associated myeloid cells provide critical support for T-ALL, in part by secreting IGF1 to activate IGF1R signaling in leukemic cells." (PMID 37805579, 2023). "Taken together, these clinical findings supported the interplay between YAP and IGF-1/IGF-1R pathway in tumor progression." (PMID 37081542, 2023). "MCL1 methylation has been associated with poor overall survival in KIRC patients, while IGF1R and CCND1 methylation have been linked to tumor aggressiveness." (PMID 37744271, 2023). "In CRC, the effects of the complex interactions of autophagy and IGF-1/IGF-1R signaling are expressed more clearly at the stage of tumor progression, in neoplastically transformed cells." (PMID 36835075, 2023). "IGF studies have indicated oncogene transformation, tumor proliferation, and tumor growth regulation by type 1 IGF receptor (IGF-1R), IGF-1, and insulin, identifying IGF signaling a viable therapeutic target." (PMID 37373357, 2023). "High expression of insulin/IGF1R positively correlated with a high level of infiltration of macrophages in the tumor, as well as advanced tumor stages." (PMID 37237509, 2023). "Linsitinib, a small-molecule tyrosine kinase inhibitor (TKI), blocks autophosphorylation of IGF1R/IR and exerts promising anti-tumor activity." (PMID 36831374, 2023).